PXYLP1 (2-phosphoxylose phosphatase 1)
Description:
Responsible for the 2-O-dephosphorylation of xylose in the glycosaminoglycan-protein linkage region of proteoglycans thereby regulating the amount of mature glycosaminoglycan (GAG) chains. Sulfated glycosaminoglycans (GAGs), including heparan sulfate and chondroitin sulfate, are synthesized on the so-called common GAG-protein linkage region (GlcUAbeta1-3Galbeta1-3Galbeta1-4Xylbeta1-O-Ser) of core proteins, which is formed by the stepwise addition of monosaccharide residues by the respective specific glycosyltransferases. Xylose 2-O-dephosphorylation during completion of linkage region formation is a prerequisite for the initiation and efficient elongation of the repeating disaccharide region of GAG chains.
Synonyms: ACPL2; HEL124; XYLP; FLJ23751
Tractability: Antibody: UniProt predicts a signal peptide or a membrane-spanning region. PROTAC: ubiquitination databases record sites on it.
Gene: Protein-coding gene on chromosome 3 (141,228,726 to 141,367,753, forward strand). Ensembl gene ENSG00000155893.
Subcellular location: Golgi apparatus membrane
Pathways (Reactome):
Metabolism: Glycosaminoglycan-protein linkage region biosynthesis
Gene Ontology:
Molecular function: phosphatase activity; protein binding
Biological process: chondroitin sulfate proteoglycan biosynthetic process; glycosaminoglycan biosynthetic process; positive regulation of heparan sulfate proteoglycan biosynthetic process; positive regulation of proteoglycan biosynthetic process
Cellular component: Golgi apparatus; Golgi membrane
Genetic constraint (gnomAD): Loss-of-function variants: 17 observed, 39.9 expected, observed/expected ratio (o/e) 0.43, 90% interval 0.29 to 0.64. The upper end of that interval is the gene's LOEUF score, 0.64, which puts it in group 2 of 6, group 1 being the genes least tolerant of losing a copy. Missense variants: 511 observed, 643.37 expected, observed/expected ratio (o/e) 0.79, 90% interval 0.74 to 0.86. Synonymous variants: 221 observed, 245.75 expected, observed/expected ratio (o/e) 0.9, 90% interval 0.81 to 1.
Homologues: Orthologues: chimpanzee PXYLP1 (99% identical), macaque PXYLP1 (98% identical), dog PXYLP1 (94% identical), pig PXYLP1 (94% identical), rabbit PXYLP1 (91% identical), guinea pig PXYLP1 (90% identical), mouse Pxylp1 (89% identical), rat Pxylp1 (89% identical), tropical clawed frog pxylp1 (68% identical), zebrafish pxylp1 (54% identical), Drosophila melanogaster CG15385 (28% identical), Caenorhabditis elegans ZK792.1 (21% identical). Paralogues in human: ACP2 (19% identical), ACP4 (18% identical), ACP6 (18% identical), ACP3 (17% identical), FRA10AC1 (7% identical).
Diseases named in the same sentence as PXYLP1 in open-access papers:
PXYLP1 is named in the same sentence as 6 diseases in open-access papers, as found by Europe PMC text mining. Sharing a sentence is not in itself a finding about the gene and the disease.
PXYLP1 shares sentences with these, for which no sentence is quoted: infection (2 papers); aspergillosis (1); atherosclerosis (1); bladder cancer (1); cancer (1); osteoarthritis (1).